TERC (telomerase RNA component)
Diseases named in the same sentence as TERC in open-access papers (continued):
Sharing a sentence is not in itself a finding about the gene and the disease.
prostate carcinoma (5 papers, 2016 to 2023). A carcinoma that arises from epithelial cells of the prostate gland. "TERC, the telomerase RNA component, part of the telomerase, could proliferate prostate cancer cells." (PMID 34336652, 2021). "Likewise, consistent overexpression of TERC has been reported in prostate cancer, and MYC mediated down-regulation of TERC has been achieved in several cancer cell lines, speculating its potential therapeutic use." (PMID 33430133, 2021).
thyroid cancer (5 papers, 2022 to 2024). "In a number of TERT-expressing malignancies, TERC overexpression drives tumor progression, as well as in aggressive thyroid carcinomas, where its upregulation is independently associated with progression-free survival." (PMID 38339237, 2024). "The results of this study reinforce the role of TERT upregulation together with other components of telomerase holoenzyme complex, such as TERC, as prognostic factors and preferential immortalization mechanism in thyroid cancer." (PMID 35979662, 2022). "Of note, the half‐life of TERC RNA is more than 2 weeks in TERT‐positive, non‐thyroid cancer cells, and consistently, TERC was observed to be more enriched in primary tumours across the TCGA pan‐cancers." (PMID 36394204, 2022).
non-small cell lung carcinoma (4 papers, 2013 to 2025). A group of at least three distinct histological types of lung cancer, including non-small cell squamous cell carcinoma, adenocarcinoma, and large cell carcinoma. "It was previously confirmed that TERC was amplified in non-small-cell lung carcinoma, and TERC based therapies have the potential function to promote apoptosis of the cancer cells with a high specificity." (PMID 35719385, 2022).
renal cell carcinoma (4 papers, 2017 to 2023). "Wu and co-authors found that TERC rs35073794 was associated with 2.4-fold increased odds of renal cell carcinoma (RCC) occurrence in an allele model (A/G) (OR =2.39, 95% CI = 0.99–5.80, p = 0.047)." (PMID 37762804, 2023). "Wu and co-authors found that TERC rs35073794 is associated with an increased risk of renal cell carcinoma (RCC) in a codominant model (OR 2.61 (1.01–6.76), p = 0.045)." (PMID 35892421, 2022). "Finally, the associations between TERC and TERT polymorphisms and clinical parameters of renal cell cancer had been further investigated." (PMID 29100352, 2017).
bone marrow failure syndrome (3 papers, 2011 to 2018). "Through mutation screening in patients with DC and related bone marrow failure syndromes, we have identified 23 novel mutations in core components of telomerase: 11 in TERC, 8 in TERT and 4 in DKC1." (PMID 21931702, 2011). "In addition, while the transplantation experiment in mouse HSCs are evidence of the impact of HuR-regulated TERC methylation in bone marrow failure syndromes, the RNA methyltransferase catalyzing the C106 methylation and the reader of C106 methylation await identification." (PMID 29880812, 2018).
coronary artery disease (3 papers, 2016 to 2022). "Furthermore, genome-wide association studies of adult leukocyte TL (LTL) identified 7 single-nucleotide variations (ACYP2, NAF1, OBFC1, RTEL1, TERC, TERT, ZNF208) linked with LTL that mutually project towards an increased risk for coronary artery disease." (PMID 35930283, 2022).
Diabetes (3 papers, 2021 to 2025). "In the TERC gene, the CC genotype was predominantly observed in newborns of parents with diabetes [16 (79%)] and COVID-19 [3 (60%)], though the association was not statistically significant (p = 0.33)." (PMID 41168774, 2025). "Analysis of the TERC and TERT genes revealed a high frequency of the CC genotype in newborns of parents with chronic diseases, particularly diabetes [ TERC: 16 (79%)] (p = 0.079), TERT: 10(50%) (p = 0.00)]." (PMID 41168774, 2025).
Fanconi anemia (3 papers, 2017 to 2025). Fanconi anemia (FA) is a hereditary DNA repair disorder characterized by progressive pancytopenia with bone marrow failure, variable congenital malformations and predisposition to develop hematological or solid tumors. "At our single institution, we had a yield of 14% (6/43) for patients with MDS or AML who were found to have a PV predisposing to myeloid disease (Fanconi Anemia, DKC1, DDX41, GATA2, TERC, and RUNX1)." (PMID 40936482, 2025).
hepatocellular carcinoma (3 papers, 2021 to 2023). A malignant tumor that arises from hepatocytes. "In this study, we aimed to assess in hepatocellular carcinoma (HCC) the cellular and extracellular expression of TERRA, the telomerase RNA subunit (TERC) and the telomerase catalytic subunit (TERT)." (PMID 35682861, 2022).
interstitial lung disease (3 papers, 2015 to 2023). A diverse group of lung diseases that affect the lung parenchyma. "Interestingly, these SNPs and their corresponding annotated genes, TERC and TERT, were associated with idiopathic forms of interstitial lung disease." (PMID 37958573, 2023).
liver cancer (3 papers, 2016 to 2020). An epithelial or non-epithelial malignant neoplasm that arises from the liver. "At the same time, MEG3 inhibits telomerase activity in human liver cancer stem cells by reducing the binding of TERT to TERC." (PMID 33256840, 2020). "Our study suggests that MEG3 promotes the expression of TERRA and thus enhances the binding of TERRA to TERT, competitively inhibits the interaction of TERC with TERT, and ultimately inhibits telomerase activity in human liver cancer stem cells." (PMID 33256840, 2020). "Our previous study showed that the overexpression of H19 increases the binding of TERT to TERC and reduces the interplay between TERT with TERRA, thus enhancing the cell telomerase activity and extending the telomere length in liver cancer stem cells." (PMID 27167190, 2016). "Furthermore, MEG3 reduces the binding of TERC to TERT, thereby further inhibiting the activity of telomerase in human liver cancer stem cells." (PMID 33256840, 2020).
liver disorder (3 papers, 2009 to 2022). A disease involving the liver. "Careful review of the family histories of patients with IPF and a TERT or TERC mutation may identify individuals with mild manifestations of DC, such as macrocytosis, mild cytopenias, avascular necrosis, cancer, or liver disease." (PMID 21676225, 2011). "In a cohort of 121 individuals with telomeropathies and variants in TERT, TERC, and TINF2, 40% were found to have some extent of liver disorder." (PMID 36311538, 2022).
myelodysplastic syndrome (3 papers, 2014 to 2021). A clonal hematopoietic disorder characterized by dysplasia and ineffective hematopoiesis in one or more of the hematopoietic cell lines. "Additionally, inherited changes in telomere length as a result of mutations in the telomere maintenance genes TERT and TERC have been identified in four HM families with myelodysplastic syndrome and acute myeloid leukemia (MDS-AML)." (PMID 25351806, 2015). "Bone marrow failure from AA or myelodysplastic syndrome (MDS) may occur as an isolated manifestation of TBD, most commonly due to TERT or TERC mutations." (PMID 34050178, 2021). "A previous study of mean relative telomere length in familial myelodysplastic syndrome MDS-AML has shown that affected individuals from four small families had shorter telomeres concurrent with mutations in the telomerase gene TERT and its RNA component TERC." (PMID 25351806, 2015).
rheumatoid arthritis (3 papers, 2020 to 2023). A chronic, systemic autoimmune disorder characterized by inflammation in the synovial membranes and articular surfaces. "Impaired TERT or TERC expression in T cells are involved in the pathogenesis of rheumatoid arthritis." (PMID 32366311, 2020). "In addition, telomerase insufficiency and shorter TL due to defective TERT and TERC expression were observed in naïve CD4 T cells from patients with rheumatoid arthritis, through which premature senescence of T cell subsets occurred and subsequent autoimmunity was triggered." (PMID 32366311, 2020).
squamous cell carcinoma (3 papers, 2014 to 2025). A carcinoma arising from squamous epithelial cells. "SOX2 and TERC gene amplifications are common in all squamous cell carcinomas and their detection in early stages could be crucial for early detection and more accurate prognosis." (PMID 24410919, 2014). "In conclusion, SOX2 and TERC gene amplifications are common in all squamous cell carcinomas, and their detection in early stages could be crucial for the detection and moreaccurate prognosis of OSCCs." (PMID 24410919, 2014). "The two remaining cancer associated genes amplified from 3q26—MECOM, encoding for the transcription factor EVI1, and TERC, encoding for the human telomerase RNA component—are not correspondingly overexpressed at the mRNA level in 3q26-amplified squamous cell cancers." (PMID 34436017, 2021).
squamous cervical cancer (3 papers, 2012 to 2021). "Amplicons of TERC and CLDN1 were also tested by FISH using a BAC probe in the cervical squamous cell carcinoma tissue microarray." (PMID 27974683, 2016). "SOX2 and PRKCI display lower levels of mRNA over-expression in 3q26-amplified squamous cervical cancers, while MECOM and TERC show no over-expression." (PMID 34436017, 2021).
telomere syndrome (3 papers, 2019 to 2023). Accelerated aging syndromes often caused by inheritable gene mutations resulting in decreased telomere lengths. "TERC and TERT were initially the only genes tested in familial pulmonary fibrosis or telomere syndrome; other TRGs such as RTEL1 or PARN were later included in the NGS panel." (PMID 31796085, 2019).
alopecia (2 papers, 2016 to 2017). Hair loss usually from the scalp. "Consistently, late‐generation (G3 and beyond) TERT or TERC‐deficient mice (TERT−/− and TERC−/−, respectively) are short living and show reduced fertility, early alopecia, kyphosis, anemia, and lymphopenia." (PMID 26968134, 2016).
Alzheimer disease (2 papers, 2018 to 2022). A progressive, neurodegenerative disease characterized by loss of function and death of nerve cells in several areas of the brain leading to loss of cognitive function such as memory and language. "Recently, it was reported that three polymorphisms (rs12696304, rs3772190, rs16847897) of the telomerase RNA component (TERC) gene were associated with Alzheimer's disease (Scarabino, Broggio, Gambina, Pelliccia, & Corbo, 2017)." (PMID 29992774, 2018).
atherosclerosis (2 papers, 2016 to 2020). A disease characterized by the build-up of fatty material and calcium deposition in the arterial wall resulting in partial or complete occlusion of the arterial lumen. "Our findings suggest that TERC variants might impact early life TL attrition in hematopoietic cells and contribute later to the pathogenesis of atherosclerosis." (PMID 32486379, 2020).
breast tumor (2 papers, 2017 to 2023). "Paradoxically, DKC1 overexpression correlates with disease progression and poor prognosis in many sporadic cancers, such as prostate and breast tumors, and DKC1 levels also associate with higher levels of TERC expression and telomerase activity in some of these tumors." (PMID 36732018, 2023). "A total of 4 genes (RAD50, RTEL, TERC and TRF1) showed significant hyper-methylation in breast tumor tissues." (PMID 28424414, 2017).
cervical (2 papers, 2012 to 2022). "We measured the genomic amplification rates and the patterns of human telomerase RNA gene (TERC) and C-MYC in the liquid-based cytological specimens to evaluate the diagnostic characteristics for the detection of high-grade cervical lesions." (PMID 22500694, 2012). "Current results suggest that a combination of RNAscope positive signals of TERC and HPV high-risk subtype signals in more than 10 cells (cytoplasm or nucleus) may connect with cervical lesion fast progression which deserves highly attention." (PMID 35073959, 2022).
dysplasia (2 papers, 2006 to 2025). A usually neoplastic transformation of the cell, associated with altered architectural tissue patterns. "Studies have shown that TERC expression is elevated in 20–21% of mild dysplasia (CIN I), 50–68% of moderate dysplasia (CIN II), 81–82% of severe dysplasia (CIN III), and 95–100% in invasive cancers." (PMID 40025596, 2025).
endometrial carcinoma (2 papers, 2024 to 2025). A malignant tumor arising from the epithelium that lines the cavity of the uterine body. "For example, endometrial cancer is characterized by intrachromosomal amplification of ESR1, KRAS, PIK3CA, ERBB2, TERC, MYC, CCNE1." (PMID 41415205, 2025).
gastric cancer (2 papers, 2022 to 2023). A primary or metastatic malignant neoplasm involving the stomach. "Although this study is the first to report TERC hypermethylation and sponging of the tumour-suppressor miRNA-320 family in PCa, similar TERC oncogenic mechanisms have been reported in gastric cancer, where TERC was shown to sponge miR-423-5p, thus promoting the proliferation of gastric cancer." (PMID 37754243, 2023).
ischemic stroke (2 papers, 2017 to 2019). A stroke disorder caused by obstruction of blood flow to the brain, due to thrombotic (local blood clot formation) or embolic (due to a blood clot or other material traveling from another site) event. "To elucidate the association between LTL variation and ischemic stroke (IS) risk, we selected ten single nucleotide polymorphisms (SNPs) in three genes (TERC, TERT and RTEL1) that previously reported link to LTL, and genotyped SNPs of these genes in a case-control study." (PMID 28057933, 2017). "Our results revealed that polymorphisms in TERC and TERT genes have an association with susceptibility risk of ischemic stroke in a Chinese Han population." (PMID 28057933, 2017). "Taken together, our results suggest a potential association between LTL related TERC, TERT gene variants and ischemic stroke risk." (PMID 28057933, 2017). "Cumulatively, our findings provide evidence that polymorphisms in TERC and TERT genes variation are associated with increased ischemic stroke risk." (PMID 28057933, 2017). "We hypothesize that these loci variant of the TERC and TERT genes could have shortened LTL, leading to increased possibility of having ischemic stroke." (PMID 28057933, 2017). "TERC and TERT variants were found linked to ischemic stroke risk." (PMID 28057933, 2017). "Based on the qPCR results, three LncRNAs (SCARNA10, TERC, LINC01481) exhibited higher expression (p < 0.01), and three LncRNAs (FLJ23867, H3F3AP6, TNPO1P1) exhibited lower expression (p < 0.05) in ischemic stroke patient PBMCs than in healthy control PBMCs." (PMID 30774621, 2019).
osteosarcoma (2 papers, 2018 to 2022). A usually aggressive malignant bone-forming mesenchymal neoplasm, predominantly affecting adolescents and young adults. "To test the interaction of TERC with HuR in cells, we employed human osteosarcoma U2OS cells, which do not express endogenous human TERT (hTERT) or TERC30." (PMID 29880812, 2018).
pancreatic cancer (2 papers, 2021 to 2022). "The results showed that the interaction of TERT and TERC decreased after knockdown of LDHB, which suggested that LDHB regulates telomerase activity in pancreatic cancer cells by affecting the assembly of TERT and TERC." (PMID 35669414, 2022).
Sepsis (2 papers, 2020 to 2022). Sepsis is defined as life-threatening organ dysfunction caused by a dysregulated host response to infection. "The expression of catalytic TERT remained unchanged across the cell types and groups, whereas TERC expression was significantly upregulated in the CD4+ T cells of sepsis patients (* p < 0.05)." (PMID 32825352, 2020).
systemic sclerosis (2 papers, 2018 to 2023). A chronic disorder, possibly autoimmune, marked by excessive production of collagen which results in hardening and thickening of body tissues. "We report here the first case of isolated PPFE in a caucasian patient with systemic sclerosis (SSc) who does not carry TERT and TERC mutations." (PMID 29776440, 2018).
viral infection (2 papers, 2022 to 2026). "Oxidative stress, DNA damage, or viral infection are known to alter TERC trafficking, and METTL3 participates in these processes." (PMID 41456942, 2026).
astrocytoma (1 paper, 2019). "Conversely, when TERC was depleted by siRNAs in human astrocytoma B2–17cells (siRNA with a scramble sequence was used as a control), both the expression and secretion level of cytokines significantly decreased." (PMID 31294790, 2019).
bacteremia (1 paper, 2023). "Previously, we have shown that this cryptic operon is highly associated with Kp pneumonia and bacteremia in colonized patients, and further work demonstrated that this association was due to a TerC-dependent fitness advantage that is conferred in the gut." (PMID 36651775, 2023).
Barrett adenocarcinoma (1 paper, 2014). An adenocarcinoma arising from Barrett metaplastic epithelium in the esophagus. "In the present study we sought to examine the frequency and potential clinical relevance of telomerase complex mutations in sporadic esophageal carcinomas after identifying a unique germline TERC deletion in a patient with Barrett's adenocarcinoma." (PMID 24983628, 2014).
Barrett esophagus (1 paper, 2009). Esophageal lesion lined with columnar metaplastic epithelium which is flat or villiform. "The proband (Subject B-II-3), a 57-year-old man heterozygous for a novel TERC nucleotide 341–360 deletion not found in 188 controls, presented a six-year history of Barrett's esophagus and recently worsening dysphagia." (PMID 19936245, 2009).
brain tumour (1 paper, 2014). "Although we found minimal changes in TERT or TERC (data not shown) expression in MST-312 treated brain tumour cells, which corroborate with the minimal effects of MST-312 in the TERT protein expression, we observed down-regulation in proteins reported to have roles in telomerase regulation." (PMID 25307264, 2014).